CDH19 (cadherin 19)
Description:
Cadherins are calcium-dependent cell adhesion proteins. They preferentially interact with themselves in a homophilic manner in connecting cells; cadherins may thus contribute to the sorting of heterogeneous cell types.
Synonyms: CDH7L2; CDH7
Tractability: Antibody: its Gene Ontology location is reachable by antibodies, with high confidence; UniProt places it where antibodies can reach, with medium confidence; UniProt predicts a signal peptide or a membrane-spanning region. PROTAC: ubiquitination databases record sites on it.
Gene: Protein-coding gene on chromosome 18 (66,501,083 to 66,604,438, reverse strand). Ensembl gene ENSG00000071991.
Subcellular location: Cell membrane
Pathways (Reactome):
Cell-Cell communication: Regulation of CDH19 Expression and Function
Gene Ontology:
Molecular function: beta-catenin binding; cadherin binding; calcium ion binding
Biological process: adherens junction organization; calcium-dependent cell-cell adhesion; cell migration; cell morphogenesis; cell-cell adhesion mediated by cadherin; cell-cell junction assembly; cell adhesion; cell-cell adhesion; homophilic cell-cell adhesion
Cellular component: adherens junction; catenin complex; plasma membrane; membrane
Genetic constraint (gnomAD): Loss-of-function variants: 28 observed, 34.75 expected, observed/expected ratio (o/e) 0.81, 90% interval 0.6 to 1.11. The upper end of that interval is the gene's LOEUF score, 1.11, which puts it in group 4 of 6, group 1 being the genes least tolerant of losing a copy. Missense variants: 679 observed, 657.16 expected, observed/expected ratio (o/e) 1.03, 90% interval 0.97 to 1.1. Synonymous variants: 232 observed, 231.69 expected, observed/expected ratio (o/e) 1, 90% interval 0.9 to 1.12.
Homologues: Orthologues: chimpanzee CDH19 (99% identical), macaque CDH19 (97% identical), dog CDH19 (87% identical), pig CDH19 (86% identical), rabbit CDH19 (81% identical), guinea pig CDH19 (80% identical), rat Cdh19 (76% identical), mouse Cdh19 (75% identical), tropical clawed frog cdh19 (51% identical). Paralogues in human: CDH7 (51% identical), CDH20 (49% identical), CDH9 (48% identical), CDH10 (48% identical), CDH6 (47% identical), CDH12 (47% identical), CDH18 (47% identical), CDH8 (46% identical), CDH11 (46% identical), CDH22 (44% identical), CDH24 (40% identical), CDH5 (36% identical), and 21 more.
Diseases named in the same sentence as CDH19 in open-access papers:
CDH19 is named in the same sentence as 26 diseases in open-access papers, as found by Europe PMC text mining. Sharing a sentence is not in itself a finding about the gene and the disease. The quoted sentences say what the papers report.
breast carcinoma (6 papers, 2014 to 2025). "The role of the CYP2C19 deletion allele, as well as that of the CDH19 deletion, in breast cancer predisposition warrants further studies and the obtained results should be replicated with larger and independent case–control cohorts." (PMID 25466287, 2014). "Based on their biological functions and recurrence, two of the previously identified deletion alleles disrupting CYP2C19 and CDH19 genes, respectively, were hypothesized to play a role in breast cancer predisposition also in the general population." (PMID 25466287, 2014). "The carrier frequency of the CDH19 deletion was twice as high in unselected breast cancer cases as in controls but remained below statistical significance, indicating the need for larger case–control cohorts to demonstrate its association with breast cancer." (PMID 25466287, 2014). "On the contrary to this study, previous researches on breast cancer reported that hsa_circRNA_102051 was downregulated in breast cancer patients, acting as a tumor suppressor and regulating miR-197-5p/CDH19 expression." (PMID 37794386, 2023). "Cdh19 (cadherin 19) was one of the top 10 downregulated DEGs identified in SB2−/−;PyMT tumors; however, there are no reports on the role of this gene in adherent junction formation associated with breast cancer progression." (PMID 35768767, 2022). "Some studies have shown that CDH19 may be a potential candidate as an immunotherapeutic target for breast cancer patients." (PMID 35600357, 2022). "Here we have defined the exact breakpoints of six previously identified deletion alleles disrupting the CYP2C19, CDH19, CASP3, DCLRE1C, DAB2IP and ITGA9 genes, respectively, and evaluated their association with breast cancer risk and disease subtype using a Northern Finnish case–control cohort." (PMID 25466287, 2014). "Moreover, CDH19 might serve as a new target of tumorigenesis and drug development for glioblastoma stem-like cells (GSC) and can be considered an independent prognostic biomarker of lung adenocarcinoma (LUAD) and breast cancer (BC)." (PMID 36345357, 2022).
melanoma (3 papers, 2019 to 2026). A malignant, usually aggressive tumor composed of atypical, neoplastic melanocytes. "Module M4 contained regulators such as FOSL1 that are associated with C1 melanoma CDH19 and C0 melanoma BIRC7." (PMID 37435067, 2023). "Module M3 contained JUND, SOX2, THAP11, and JUN, as well as regulators for C5 Melanoma MAGEA4, C6 Melanoma GJB2, C2 melanoma EDNRB, and C1 melanoma CDH19." (PMID 37435067, 2023). "Furthermore, Ca19Mab-8 can detect CDH19 in IHC using human melanoma tissue." (PMID 41899458, 2026). "Furthermore, we found that the highest regulon activity scores of melanoma cell subtypes in M1-M4 were C4 Melanoma CORO1A (M1), C4 Melanoma CORO1A (M2), C5 Melanoma MAGEA4 (M3), and C1 Melanoma CDH19 (M4), respectively." (PMID 37435067, 2023).
cholesteatoma (2 papers, 2012 to 2016). A pathologic process characterized by the proliferation of keratinizing squamous epithelium resulting in the accumulation of keratin and cells in the middle ear and/or mastoid. "Cadherin 19 (cdh19) is another likely target gene of two HS HCSNs, down-regulation of which has been linked to the development of cholesteatoma, an expanding destructive epithelial lesion within the middle ear." (PMID 27289096, 2016). "We were able to demonstrate that two integral membrane proteins, CDH18 and CDH19, from the cadherin superfamily are down-regulated in cholesteatoma." (PMID 23285167, 2012).
glioblastoma (2 papers, 2022 to 2026). The most malignant astrocytic tumor (WHO grade IV). "Additionally, Ca19Mab-8 recognized endogenous CDH19 in the human glioblastoma cell line LN229." (PMID 41899458, 2026).
head and neck cancer (2 papers, 2012 to 2024). A primary or metastatic malignant neoplasm affecting the head and neck. "CDH19 (Cadherin-19) is of particular interest as it has been previously shown that it is down-regulated in head and neck cancer cell lines." (PMID 23285167, 2012). "The down-regulation of CDH19 might support putative involvement in head and neck cancer progression." (PMID 38307969, 2024).
bladder cancer (1 paper, 2024). "This trend implies a potential association between reduced CDH19 levels and the pathogenesis of BC, underscoring CDH19 as a promising candidate for prognostic assessments in the context of bladder cancer." (PMID 38307969, 2024).
cervical cancer (1 paper, 2013). A primary or metastatic malignant neoplasm involving the cervix. "Among the 49 PRC2 targets (defined by consistent hyper-MVPs) identified here were 10 genes of the cadherin superfamily in HPV+ HNSCC, including CDH8 and CDH13 (both also hypermethylated in cervical cancer, CDH18, CDH19, CDH23, PCDH10, PCDH15, PCDHB1, PCDHB4, and PCDHB15." (PMID 23419152, 2013).
geographic atrophy (1 paper, 2023). "To date, there are no reports of CDH19 involvement in AMD, although a recent study has demonstrated an upregulation of many proteins involved in cell adhesion and extracellular matrix (ECM) regulation in geographic atrophy patient cohort." (PMID 36645183, 2023).
ischemia (1 paper, 2021). A hypoperfusion of the BLOOD through an organ or tissue caused by a PATHOLOGIC CONSTRICTION or obstruction of its BLOOD VESSELS, or an absence of BLOOD CIRCULATION. "Under nonischemic conditions, pericytes expressed Cdh19, Cdh6, Cdh10, Cdh4, Cdh13, and Cdh5; after ischemia, the cadherin genes that were predominantly expressed were Cdh15, Cdh11, Cdh3, and Cdh2." (PMID 33726849, 2021).
major depressive disorder (1 paper, 2016). An episode of depression lasting two or more weeks without an intervening episode of mania. "The best two-point linkage within the region was found at 18q22.1 near CDH7 and CDH19 genes (LOD 3.3), and the best joint LD and linkage was found at rs11152166 (p-value 5.1*10−5, dominant model), which has previously been linked to major depressive disorder." (PMID 26909693, 2016).
neuroblastoma (1 paper, 2016). Neuroblastoma (NB) is the most common solid, extracranial childhood tumor. "As to the neuroblastoma gene network, the degrees of NTRK1 and CDH19 were much larger than those of other genes." (PMID 27349736, 2016).
pulmonary fibrosis (1 paper, 2013). Chronic progressive interstitial lung disorder characterized by the replacement of the lung tissue by connective tissue, leading to progressive dyspnea, respiratory failure, or right heart failure. "Many reports indicate that OB-cadherin contributes to EMT in pulmonary fibrosis and promotes the metastasis of several types of cancer cells, while very little information on the role of CDH19 is available." (PMID 23741434, 2013).
schwannoma (1 paper, 2013). A benign, usually encapsulated slow growing tumor composed of Schwann cells. "Cad19 (CDH19), which is only expressed in the Schwann cell precursor, is overexpressed in schwannomas (10.8-fold, p=6.54e-5)." (PMID 23354516, 2013).
tumor (8 papers, 2013 to 2024). "Mutation analyses of genes in the 18q22.1 region including CDH7 and CDH19 did not reveal any tumor specific mutations, suggesting that other mechanisms of gene inactivation are operational." (PMID 24165089, 2013). "In the TCGA CRC dataset, three genes, ACAA1, CDH19, and SCGB2A1, were downregulated in tumor tissues, whereas the other three genes were overexpressed in tumor tissues." (PMID 35909904, 2022). "CDH19 was expressed by SCLCs and RNA in situ hybridization (ISH) targeting CDH19 in an AT-PG tumor (P018-PGL3) showed staining of spindle-like cells, that were similar in morphology to S100 + cells using IHC." (PMID 36271074, 2022). "Cadherins CDH19, CDH16, CDH11 were found to be down regulated in OTSCC tumor as a read out of EMT process." (PMID 27280700, 2016). "The tumor characteristics of CDH19 deletion carriers did not significantly differ from non-carrier cases, although the carrier tumors tended to be more frequently of higher grade (7/12, 58.3%, of the tumors categorized as grade 3) than the non-carrier tumors (197/522, 37.7%)." (PMID 25466287, 2014). "This region encompasses the CDH19 and CDH7 genes, however, we could not confirm the loss of CDH19 in tumor 16 with the small deletion in 18q22.1." (PMID 24165089, 2013).
cancer (4 papers, 2013 to 2024). A tumor composed of atypical neoplastic, often pleomorphic cells that invade other tissues. "CDH19 showed the lowest expression in all 14 cancer types, while PSMB1 presented the highest expression levels." (PMID 35909904, 2022). "For example, compared to their parental epithelial cells, carcinoma cells express much less epithelial markers like CDH19." (PMID 28246385, 2017). "According to the data analyses online, we launched immunohistochemistry for CDH19 utilizing a tissue chip containing 25 paired cancer and para-cancer tissues, we found out only a few amounts of CDH19 expression in BC tissues contrast with the corresponding para-cancer tissues." (PMID 38307969, 2024). "Due to the expression changes of CDH19 and the influence of sorafenib on the histone modification profiling at its promoter during EMT, we hypothesize that CDH19 could act as another vital mediator of EMT and a novel therapeutic target for the treatment of organ fibrosis and cancer." (PMID 23741434, 2013). "We found that CDH19 and SCBB2A1 displayed negative signal intensity in the IHC stained cancer tissues, while ACAA1 showed moderate intensity in cancer tissues." (PMID 35909904, 2022).
cardiovascular diseases (1 paper, 2022). "TCF21, CDH19, XG, and NNAT might serve as feature genes for CAD, providing new insights for future research on the pathogenesis of cardiovascular diseases." (PMID 36345357, 2022). "In addition, the four feature genes identified (TCF21, CDH19, XG, and NNAT) might serve as feature genes for CAD, bringing new insights into the pathogenesis of cardiovascular diseases." (PMID 36345357, 2022).
CDH19 also shares sentences with these, for which no sentence is quoted: amyotrophic lateral sclerosis (1 paper); cutaneous melanoma (1); diaphragmatic hernia (1); gastric cancer (1); lung adenocarcinoma (1); microphthalmia (1); neurodegenerative disease (1); neurofibroma (1); Parkinson disease (1); trichotillomania (1).